DEFB123 (defensin beta 123)
Description:
Has antibacterial activity.
Synonyms: DEFB-23; DEFB23; ESC42-RELD
Tractability: Antibody: UniProt places it where antibodies can reach, with high confidence; UniProt predicts a signal peptide or a membrane-spanning region; its Gene Ontology location is reachable by antibodies, with medium confidence.
Gene: Protein-coding gene on chromosome 20 (31,440,632 to 31,450,257, forward strand). Ensembl gene ENSG00000180424.
Subcellular location: Secreted
Pathways (Reactome):
Immune System: Beta defensins; Defensins
Gene Ontology:
Molecular function: membrane destabilizing activity
Biological process: innate immune response; killing of cells of another organism; defense response to Gram-negative bacterium
Cellular component: extracellular region
Genetic constraint (gnomAD): Loss-of-function variants: 4 observed, 4.81 expected, observed/expected ratio (o/e) 0.83, 90% interval 0.4 to 1.72. That is too few expected variants to judge how well the gene tolerates losing a copy. Missense variants: 71 observed, 77.93 expected, observed/expected ratio (o/e) 0.91, 90% interval 0.75 to 1.11. Synonymous variants: 22 observed, 29.76 expected, observed/expected ratio (o/e) 0.74, 90% interval 0.53 to 1.06.
Homologues: Orthologues: chimpanzee DEFB123 (100% identical), macaque DEFB123 (96% identical), pig DEFB123 (78% identical), rabbit DEFB123 (78% identical), rat Defb36 (78% identical), mouse Defb36 (76% identical), dog DEFB123 (75% identical), guinea pig DEFB123 (72% identical). Paralogues in human: DEFB121 (46% identical), DEFB118 (40% identical), DEFB135 (37% identical), DEFB132 (36% identical), DEFB119 (34% identical), DEFB115 (33% identical), DEFB116 (33% identical), DEFB125 (33% identical), DEFB129 (30% identical), DEFB134 (30% identical), DEFB124 (28% identical), DEFB128 (28% identical), and 7 more.
Diseases named in the same sentence as DEFB123 in open-access papers:
DEFB123 is named in the same sentence as 2 diseases in open-access papers, as found by Europe PMC text mining. Sharing a sentence is not in itself a finding about the gene and the disease. The quoted sentences say what the papers report.
Sepsis (1 paper, 2013). Sepsis is defined as life-threatening organ dysfunction caused by a dysregulated host response to infection. "Another human β-defensin, DEFB123, has been shown to bind bacterial lipopolysaccharides and prevent the lethal consequences of sepsis in a mouse model." (PMID 24098648, 2013).
DEFB123 also shares sentences with these, for which no sentence is quoted: pneumonia (2 papers).